IL17A (interleukin 17A)
Diseases named in the same sentence as IL17A in open-access papers (continued):
Sharing a sentence is not in itself a finding about the gene and the disease.
Sepsis (continued). "To explore the potential role of IL-17A in sepsis, we employed severe CLP models and found elevated IL-17A concentrations in blood in CLP mice 3 h after severe CLP surgery." (PMID 23056325, 2012). "IL-17A is a proflammatory cytokine and is a mediator of neutrophil stimulation and mobilization by T lymphocytes in sepsis." (PMID 22590504, 2012). "Taking our findings together, we propose that γδ T cells first migrate to the peritoneal cavity and secrete IL-17A, which is the main source of systemic IL-17A during the early stage of sepsis." (PMID 23056325, 2012). "IL17A production is increased as an innate response to bacterial infection in human immune cells, and elevated serum IL17A levels are observed in human and animal models of sepsis." (PMID 22026963, 2011). "This peritoneal vicious cycle that includes NET formation, IL-17A, CXCL-1/CXCL-2 that may amplify sepsis-associated organ injury." (PMID 41588042, 2026). "For example, we found sepsis to induce the expression of the interleukin-17 (IL-17) a and f genes." (PMID 41565647, 2026). "Breaking this vicious cycle by inhibiting NET formation and/or IL-17A might be a promising therapeutic target for sepsis treatment." (PMID 41041553, 2025). "Studies analyzing proinflammatory cytokines, such as IL-8, IL-12, IL-17A, and IL-18, and anti-inflammatory cytokines, such as IL-4, IL-10, and IL-11, have reported no effective neutralizing antibodies to improve the outcomes of human sepsis." (PMID 40136690, 2025). "IL-17A, generally peaks later—around 12 to 24 h after sepsis initiation." (PMID 40566580, 2025). "Furthermore, IL17A production by hepatic NKT cells was significantly decreased in α-GalCer-pretreated mice during LPS/D-GalN-induced sepsis." (PMID 39355237, 2024). "Our results showed that correlates promoting the development of infectious complications in patients with sepsis-associated ARDS included SOFA score, oxygenation index, the application of vasoactive drugs, NLR, IL-4, and IL-17A, in addition to CD16brightCD62Ldim neutrophils and IL-8." (PMID 38605959, 2024). "IL-17A-mediated neutrophil infiltration in the CNS may endanger neuronal cells by releasing oxidants through the activity of iNOS and MPO, thus promoting sepsis-associated CNS dysfunction." (PMID 37175808, 2023). "The levels of proinflammatory cytokines including IL-6, IL-1β, Il-17A and TNF-α, as detected by quantitative PCR or enzyme-linked immunosorbent assay (ELISA), were decreased in lung tissue of sepsis mice upon treatment of JHD, as compared with their counterpart with no treatment." (PMID 37081964, 2023). "Increased MPO activity (considered to be a marker of neutrophilic presence) in the cerebral cortex of sepsis survivor mice could be due to increased IL-17A levels." (PMID 37175808, 2023). "Our study shows a reduction in IL-17A levels with a concurrent abatement of neuroinflammation by the ITK inhibitor, which may be responsible for the amelioration in sepsis-associated depression-like behavior." (PMID 37175808, 2023). "Sepsis-induced IL-17A signaling was greatly reduced by the ITK inhibitor." (PMID 37175808, 2023). "The ITK inhibitor mediated the downregulation of IL-17A, and subsequent oxidative stress in the CNS may protect neuronal cells from oxidative injury, which can partly mitigate sepsis-mediated behavioral problems." (PMID 37175808, 2023). "Our data show, for the first time, that the ITK inhibition strategy may counteract sepsis-mediated depression through a reduction in IL-17A signaling in the CNS." (PMID 37175808, 2023). "On the other hand, however, we could show that chronic IL-17A stimulation in the context of other neuroinflammatory diseases, such as a LPS-sepsis model or cuprizone-induced demyelination, enhances neuroinflammatory responses." (PMID 36857006, 2023). "Moreover, IL-17A+ γδ T cells have been identified as playing a protective role in polymicrobial sepsis, particularly in organ failure of the lung." (PMID 37475963, 2023).
Sepsis (continued). "However, our study is the first to demonstrate the protective effect of neutralizing IL-17A on rats with severe sepsis using an approved monoclonal antibody drug, Secukinumab." (PMID 36253831, 2022). "Our results suggest that secukinumab may inhibit the activation of the IKBα/NFκB inflammatory pathway in severe sepsis by neutralizing IL-17A." (PMID 36253831, 2022). "The role of the IL-17A-related signaling pathway in sepsis is still a research hotspot." (PMID 36253831, 2022). "In the current study, PBMC MALT1 expression was positively associated with Th17 cells, IL‐17A level in sepsis patients, but not with Th1 cells or IFN‐γ level." (PMID 35262976, 2022). "Lnc‐GAS5 negatively linked with Th17 cells and IL‐17A; negatively correlated with SOFA score, SOFA‐Respiratory system score, SOFA‐Coagulation score and SOFA‐Renal system score; negatively related to CRP and APACHE II score in sepsis patients." (PMID 35325494, 2022). "Besides, Th1 and Th17 cells were measured in PBMCs from sepsis patients by flow cytometry; IL‐17A and IFN‐γ were determined in serum from sepsis patients by ELISA." (PMID 35262976, 2022). "Partial depletion of Tregs elevated IL-17A, IL-1β, and IL-6 production and decreased IL-10 levels, leading to lower bacterial load and attenuation of lung injury in secondary P. aeruginosa infection after sepsis." (PMID 34222495, 2021). "An increase in IL-17A ILC3 is associated with the development of inflammatory bowel disease, multiple sclerosis and NEC, while a decrease in this subset is associated with the development of sepsis." (PMID 34151271, 2021). "Circulating levels of IL-17A are elevated in human and experimental sepsis." (PMID 33995408, 2021). "We also verified the role of IL-17A in sepsis-induced cardiac dysfunction and confirmed whether IL-17A participated in the effect of MCTR1 on sepsis-induced cardiac dysfunction." (PMID 33981320, 2021). "Notably, inhibition of IL-17A protected mice from both experimental sepsis and trauma/hemorrhage, consistent with a central organizing role of IL-17A in self-sustaining inflammatory networks." (PMID 34167455, 2021). "Given the similarities between ILC2s and γδ T cells in the immune system, we aimed to gain an insight into the interaction between ILC2s and γδ T cells, particularly, pertaining to the precise regulation of lung IL-17A production in sepsis, as the source of IL-17A is controversial." (PMID 33995408, 2021). "Studies suggest that IL-17A-mediated signaling orchestrates inflammatory and immune cascades by inducing proinflammatory mediators, thereby participating in preventing bacteria during sepsis." (PMID 32849528, 2020). "IL-17A-deficient mice are more susceptible to sepsis than wild-type controls, and IL-17A blockade impairs peritoneal eradication of E. coli, indicating that IL-17A might prevent sepsis in certain settings." (PMID 32849528, 2020). "IL-17A promotes excessive inflammatory cytokine production that may result in adverse outcomes in experimental sepsis." (PMID 32290120, 2020). "Interestingly, high mobility group box-1 protein (HMGB1), a crucial late biomarker of lethal systemic inflammation in sepsis, stimulates IL-17A release during myocardial I/R injury." (PMID 32849528, 2020). "Targeting IL-17A enhanced IL-10 production in peripheral blood mononuclear cells following sepsis." (PMID 32849528, 2020). "Increased circulating levels of IL-17A are observed in experimental and human sepsis." (PMID 32849528, 2020). "However, subsequent studies using mice deficient in the IL-17 receptor found opposite results, and the literature now contains numerous studies demonstrating the mixed effects of IL-17A blockade in sepsis." (PMID 31507598, 2019). "Blockade of the IL-17A/IL-17R pathway with neutralizing antibodies could suppress the CNS inflammation and microglia response, thereby partially reversing sepsis-induced cognitive dysfunction." (PMID 31686986, 2019).
Sepsis (continued). "In the current study, the significant alteration of IL-17 signaling pathways in the muscle layer in septic mice led us to hypothesize that blocking IL-17A could contribute to improving the dysmotility of the small intestine induced by sepsis." (PMID 31531179, 2019). "Additionally, neutralization of IL-17A improved the intraluminal pressure of the small intestine during sepsis." (PMID 31531179, 2019). "In addition, treatment targeting IL-17A also elevated the low mRNA expression levels of c-Kit and Ano-1, which are specific biomarkers that are expressed in ICCs and induced by sepsis." (PMID 31531179, 2019). "Moreover, sepsis caused significant activation of NF-κB and MAPK signaling, which was suppressed by treatment with IL-17A-Ab." (PMID 31531179, 2019). "Our previous study demonstrated that IL-17A derived from the γδ T cells in the peritoneal cavity entered into the circulation rapidly during the early phase of sepsis, and blockade of IL-17A alleviated the proinflammatory response and vital organ injury, thus improving the survival of septic mice." (PMID 31686986, 2019). "In addition, ATF3 expression was rapidly induced in the lung at 4 and 6 hpi, suggesting that ATF3 plays an important role in sepsis via IL-17A." (PMID 30214444, 2018). "We hypothesized that ROS can enhance secretion of IL-17A during sepsis and that hence immune cells may be critical mediators of host responses to sepsis." (PMID 27389701, 2016). "However, little was previously known about SA-AKI, although IL-17A is involved in the pathogenesis of sepsis." (PMID 27334720, 2016). "C9A mutation failed to decrease IL-17A production upon E. coli-induced sepsis determined by immunostaining." (PMID 27389701, 2016). "To investigate whether AnxA2 generally affects ROS levels in other sepsis models, we employed bacterial infection models with E. coli and P. aeruginosa to study the relationship between ROS levels and IL-17A release." (PMID 27389701, 2016). "Moreover, neutralization of IL-17A significantly decreased the IL-6 serum levels in the morphine-treated animals at 72 hours after CLP, validating the pro-inflammatory role of IL-17A during sepsis progression." (PMID 26039416, 2015). "This is the first study to provide a mechanistic insight into the opioid exacerbation of sepsis and show that neutralization of IL-17A might be an effective therapeutic strategy to manage Gram-positive sepsis in patients on an opioid regimen." (PMID 26039416, 2015). "The earlier and higher elevated IL-17A derived from γδ T cells in peritoneal fluid plays a critical role during polymicrobial severe sepsis and effect of intraperitoneal IL-17A antibody administration superior to intravenous administration on survival of severe CLP-induced septic mice." (PMID 23056325, 2012). "The intraperitoneal blockade of IL-17A decreases proinflammatory cytokine production, neutrophil infiltration, and lung injury, thereby improving septic mice survival, which provides a new potential therapy target for sepsis." (PMID 23056325, 2012). "The intraperitoneal neutralisation of IL-17A exerts protective effects against sepsis-induced organ tissue damage and lethality, which are associated with substantially reduced levels of bacteraemia and significant reductions in systemic proinflammatory cytokines." (PMID 23056325, 2012). "IL-17A is an important chemotactic cytokine for neutrophils and plays a detrimental role in sepsis." (PMID 22590504, 2012). "Multiple studies have shown that single nucleotide polymorphisms (SNPs) in important immune response genes alter susceptibility to infection and/or outcome of severe sepsis, but the role of IL17A SNPs has not yet been investigated in severe sepsis." (PMID 22026963, 2011). "Genetic factors contribute to the host defense, but the role of IL17A single nucleotide polymorphisms (SNPs) has not yet been investigated in severe sepsis." (PMID 22026963, 2011).
Sepsis (continued). "Finally, our data may also help in proposing further research into therapies employing CX3CR1 antagonists (AZD8797) or humanised monoclonal antibody of IL-17A (ixekizumab) as potential therapeutic targets in sepsis." (PMID 40433376, 2025). "To determine whether differences in DEL-1 expression observed in different tissues during neonatal sepsis reflected respective changes in IL-17A and IL-10, we measured IL-17A and IL-10 mRNA expression in tissue extracts from neonates 6 hours following exposure to CS-induced sepsis." (PMID 38263289, 2024). "Furthermore, IL-17A has been described as a main player in the immunological dysfunction during sepsis, with increased levels in serum of pediatric and adult patients during early stage of sepsis, making it an attractive biomarker and therapeutic target." (PMID 36439175, 2022). "Furthermore, IL-17A has been shown to induce TEC apoptosis in AKI in sepsis." (PMID 35872775, 2022). "Although IL-17A is associated with the initiation of systemic inflammatory response syndrome in AP, IL-17A may not be the cause of sepsis in the second stage (pancreatic infection and necrosis)." (PMID 34594321, 2021). "However, it remains unclear whether lung ILC2s secrete IL-17A or regulate other cells to secret IL-17A in a setting of sepsis." (PMID 33995408, 2021). "Moreover, anti-IL-17A could protect the lungs in lipopolysaccharide (LPS)-induced acute lung injury and improve survival in polymicrobial sepsis induced by cecal ligation and puncture (CLP)." (PMID 33981320, 2021). "Importantly, LE was associated with a decrease in IL-17A-producing ILC3 at 2-weeks of life and re-colonization with a normal microbiome immediately after antibiotic exposure resulted in an increase in ILC3 and a partial rescue from late-onset sepsis." (PMID 32737397, 2020). "We selected some of the TNF-α and IL-17A targeting miRNAs based on knowledge of their involvement in modulating inflammatory response and using RT-qPCR, we confirmed upregulation of these miRNAs in sepsis intestinal epithelial EVs, compared with control intestinal epithelial EVs." (PMID 33182773, 2020). "Therefore, the HMGB1/IL-17A axis may play a key role in myocardial dysfunction resulted from sepsis." (PMID 32849528, 2020). "Our findings revealed the important role of the IL-17 signaling pathway in the small intestine during sepsis and suggested that targeting IL-17A might be a promising strategy for treating dysfunction of the small intestine during sepsis." (PMID 31531179, 2019). "The upregulated levels of IL-17A during sepsis might be harmful to the small intestine." (PMID 31531179, 2019). "By using the neutralizing antibodies to IL-17A or IL-17R, we hypothesized that blockade of the IL-17A/IL-17R pathway on microglial cells could suppress the potent cerebral inflammatory response, thereby preventing the cognitive impairment during sepsis." (PMID 31686986, 2019). "Additionally, blockade of IL-17A results in improved survival, suggesting that Th17 cells may negatively contribute to sepsis mortality." (PMID 30226896, 2018). "However, the role of the IL-17A pathway in sepsis is controversial." (PMID 23056325, 2012). "However, during CLP sepsis, the level and role of IL-17A within the peritoneal fluid is unclear." (PMID 23056325, 2012). "Since proinflammatory cytokine overproduction is indicative of sepsis, we evaluated the levels of TNF‐α, IFN‐γ, IL‐1α, IL‐1ß, IL‐6, IL‐10, IFN‐ß, IL‐17A, IL‐23, IL‐27, MCP‐1, IL‐12p70, and GM‐CSF in the serum at 16 h after LPS‐induced septic shock." (PMID 39482884, 2025). "The MAIT cell‐activating cytokines IL‐12, IL‐15 and IL‐18, as well as TNF, IFNγ and IL‐17A, cytokines known to be produced by MAIT cells, were elevated in the plasma of sepsis patients as well as non‐sepsis patients, compared with non‐infected controls." (PMID 40041474, 2025).
Sepsis (continued). "We further explain the mechanistic basis of the discrepancy in DEL-1 expression between neonates and adults in sepsis, by demonstrating that DEL-1 is under the control of IL-10 and particularly of the IL-10 to IL-17A ratio." (PMID 38263289, 2024). "The cecal gene expression of IL-6, IL-1β, TNF-α, IL-17A, IL-22, and CRAMP (homologue of human cathelicidin LL-37) was significantly elevated in mice with gut-derived P. aeruginosa sepsis." (PMID 38790988, 2024). "Meanwhile, the cytokine levels in the plasma of rat including IL‐17A, TNF, and IL‐6, the critical factors for the disorder of immune system and high mortality in sepsis model, were measured by flow cytometry analysis." (PMID 38023725, 2023). "Among the molecular variables, IL-1Ra, IL-17A, CCL19, CX3CL1 and TNF were significantly higher in septic patients compared to the infection non-sepsis group." (PMID 37691028, 2023). "TLR9 in DCs can also be activated by mitochondrial DNA (mtDNA), by mediating IL-17A production in γδ T cells, thus promoting the development of AKI during sepsis." (PMID 35872775, 2022). "In another study with mouse model of sepsis, EVs from intestinal luminal lavage were enriched with miRNAs, which putatively targeted TNF-α and IL-17A." (PMID 35187084, 2022). "MALT1 expression (p = 0.010), Th1 cells (p = 0.010), Th17 cells (p = 0.038), and IL‐17A (p = 0.012), except for IFN‐γ (p = 0.102), elevated in sepsis deaths compared with sepsis survivors." (PMID 35262976, 2022). "One hundred‐one sepsis patients were enrolled for detecting lnc‐GAS5, Th1 cells, Th17 cells, IFN‐γ and IL‐17A." (PMID 35325494, 2022). "In sepsis, NMU acting through NMUR1 in lung ILC2s initiates the ILC2 activation, which, in turn, promote IL-17A-producing γδ T cell expansion and secretion of IL-17A." (PMID 33995408, 2021). "It has been reported that serum cytokines such as IL-1β, IL-6, IL-8, IL-10, IL-12, IL-17A, IL-18, interferon gamma (IFN-γ), and TNF-α are elevated in sepsis, but some of these cytokines are also elevated in FMF patients." (PMID 34654467, 2021). "In addition, targeting IL‐18/IL‐1/IL‐17A axis may improve outcomes for human neonates with sepsis." (PMID 33378581, 2021). "Here, we investigated the ability of intestinal epithelial EVs in sepsis to suppress TNF-α, and IL-17A based on the assumption that such a capability would primarily be mediated by exosomal miRNAs." (PMID 33182773, 2020). "Physiological levels of IL-17A in type 3 innate lymphoid cells (ILCs) accelerate G-GSF production and neutrophil recruitment, protecting the host against sepsis." (PMID 32849528, 2020). "In the ileal tissues of healthy mice, sepsis EVs (S-EVs) downregulated messages of the pro-inflammatory cytokines including TNF-α, IL-1β, IL-6, IL-17A, and IL-22." (PMID 33182773, 2020). "Model mice were treated with IL-33 or its receptor ST2 in order to determine the effects of IL-33 on IL-17A, IL-22, and PGE2 in septicemia." (PMID 33178181, 2020). "MicroRNA (miRNA) profiling and reverse transcription and quantitative polymerase chain reaction (RT-qPCR) revealed a sepsis-induced exosomal increase in multiple miRNAs, which putatively target TNF-α and IL-17A." (PMID 33182773, 2020). "In the current study, a septicemic mouse model was established by infecting mice with S. epidermidis (ATCC 12228) in order to analyze the effects of IL-33 on the development of septicemia and the production of PGE2, IL-17A, and IL-22." (PMID 33178181, 2020). "Considering all these evidence, our study supports the contention that sepsis-enhanced functional miRNAs in IEC EVs possess the ability to regulate TNF-α and IL-17A expression in the gut." (PMID 33182773, 2020). "Anti-IL-17A antibodies downregulate CCL3, CXCL1, and IL-6 in cardiomyocytes of mice with sepsis induced by CLP, suggesting that IL-17A contributes to sepsis-induced cardiomyopathy." (PMID 32849528, 2020).